CDKL5 (cyclin dependent kinase like 5)
Diseases named in the same sentence as CDKL5 in open-access papers (continued):
Sharing a sentence is not in itself a finding about the gene and the disease.
epilepsy (continued). "In this analysis, only two studies were targeted to analyze the efficacy of KD in CDKL5-related epilepsy." (PMID 36274176, 2022). "The definite responder rate to KD in CDKL5-related epilepsy was 18%, and the gastrointestinal adverse reactions were probably common in these patients." (PMID 36274176, 2022). "Spontaneous epilepsy has only recently been observed in aged heterozygous female mice and in male mice harbouring the conditional knock-out (KO) of Cdkl5 in glutamatergic forebrain neurons." (PMID 36613509, 2022). "We performed a meta-analysis on KD in patients with CDKL5-related epilepsy to provide relatively reliable evidence and a data basis for future research." (PMID 36274176, 2022). "Further studies with higher quality are needed to confirm the safety of KD in CDKL5-related epilepsy." (PMID 36274176, 2022). "CDKL5 deficiency disorder (CDD, OMIM 300672), also known as CDKL5 encephalopathy, CDKL5 epileptic encephalopathy, or CDKL5-related epilepsy, is a rare neurological disorder." (PMID 36274176, 2022). "All the studies mentioned the efficacy of KD in CDKL5-related epilepsy, and four of them clearly defined the efficacy, with an overall responder rate of 11.8% (4/34)." (PMID 36274176, 2022). "The systematic review and meta-analysis showed that the definite responder rate of KD in CDKL5-related epilepsy was only 18.0%." (PMID 36274176, 2022). "The purpose of this meta-analysis was to determine the efficacy of KD in CDKL5-related epilepsy and to evaluate its possible adverse reactions." (PMID 36274176, 2022). "The clinical features of CDKL5-related disorder include early epilepsy onset, global developmental delay, involvement of gross motor skills, abnormal muscle tone, sleep disorders, gastrointestinal problems and breathing irregularities." (PMID 35299616, 2022). "The incidence of gastrointestinal adverse reactions was relatively higher in the patients with CDKL5-related epilepsy during the KD." (PMID 36274176, 2022). "Updated recommendations of the International Ketogenic Diet Study Group in 2018 suggested that KD was moderately beneficial for CDKL5-related epilepsy." (PMID 36274176, 2022). "Further prospective studies with large samples are needed to confirm the efficacy of KD in CDKL5-related epilepsy." (PMID 36274176, 2022). "Epilepsy in CDKL5 encephalopathy being typically unresponsive to conventional therapy is associated with severe psychomotor development delay." (PMID 37193389, 2022). "On the other hand, CDKL5 epilepsy starts following the neonatal period with median age of 1.5 month, once GABA transmission particularly involved in sleep has become inhibitory." (PMID 37193389, 2022). "CDKL5-related epilepsy is a rare nervous system disease, and high-quality evidence from studies with large samples, prospective cohorts or randomized control trials is relatively difficult to achieve." (PMID 36274176, 2022). "CDKL5 is a gene causally linked to CDKL5 deficiency disorder (CDD), where patients develop intellectual delay and epilepsy." (PMID 35359577, 2022). "Additional high-quality studies are needed to confirm the efficacy and tolerance of KD in CDKL5-related epilepsy." (PMID 36274176, 2022). "More recently, a similar disparity between PL and sVEP acuities were described in 11 patients with a genetically confirmed seizure disorder CDKL5 and CVI." (PMID 34776912, 2021). "For epilepsy, limited studies have also implied a role of MEs via ME-mediated genomic rearrangements in CDKL5 and ALDH7A1 and de novo somatic L1 insertions biased toward epilepsy-associated genes." (PMID 34868252, 2021). "Mosaicism is increasingly appreciated as a factor in the occurrence and variability of genetic disease, with mosaic pathogenic variants found in up to 8% of affected probands with other X-linked neurodevelopmental disorders such as CDKL5 and PCDH19 epilepsy." (PMID 34828275, 2021).
epilepsy (continued). "In this context, single-gene epilepsies are mainly composed of mutations in the PRRT2, SCN1A, KCNQ2, SLC2A1, or CDKL5 genes." (PMID 33888873, 2021). "CDKL5 deficiency disorder (CDD), a severe neurodevelopmental disorder characterized by early onset epilepsy, intellectual disability, and autistic features, is caused by mutations in the CDKL5 gene." (PMID 34238328, 2021). "By real-time PCR, we detected a down-regulation of Arx, Cdkl5, and Dclk1 genes, human homologues of which are involved in etiology of epilepsy." (PMID 31698854, 2019). "Mosaicism in the proband has been reported in other genes such as PCDH19 (8.3%, 6/73), SCN1A (1.3%, 4/320), SCN2A (6.4%, 7/110), and CDKL5 (8.8%, 8/91), according to a recent large‐scale study of epilepsy‐related neurodevelopmental disorders." (PMID 30891744, 2019). "The systematic search took place in February/2017 and updated in December/2017 using the keywords “epilepsy” or “Dravet” or “Lennox-Gastaut” or “CDKL5” combined with “Cannabis,” “cannabinoid,” “cannabidiol,” or “CBD” resulting in 199 papers." (PMID 30258398, 2018). "We find current evidence for this preferential enrichment among six epilepsy genes: CDKL5 (P = 1.1 × 10−12), KCNQ2 (P = 1.1 × 10−23), PCDH19 (P = 0.003), SCN1A (P = 9.7 × 10−9), SCN2A (P = 1.9 × 10−4), and SCN8A (P = 3.5 × 10−4)." (PMID 28864458, 2017). "Epilepsy in CDKL5 disorder is characterized by complex partial seizures, infantile spasms, myoclonic and tonic seizures." (PMID 27080038, 2016). "The onset of epilepsy is much earlier (1.4 months) in the CDKL5 disorder than in Rett syndrome (4.9 years)." (PMID 27080038, 2016). "Epilepsy was also common but relatively easy to control as compared with CDKL5 related disorder, another Angelman-like Syndrome." (PMID 26942024, 2016). "Consistent with previous studies, the early onset of epilepsy (median age of onset 6 weeks) was a key feature of CDKL5 disorder." (PMID 27080038, 2016). "We interpret these findings as an indication that Cdkl5 impacts on the development of epilepsy in humans in a manner significantly different from mice." (PMID 24838000, 2014). "The present study investigated mutations in CDKL5 in a cohort of patients with epilepsy and RTT or other RTT-like phenotypes to improve the diagnostic criteria for these patients and to clarify the pathological mechanisms of CDKL5 mutations." (PMID 22867051, 2012). "SUDEP is reported in CDKL5 deficiency disorder, but the risk and frequency of SUDEP in this monogenic epilepsy is unknown." (PMID 40381056, 2025). "In the same way, several DEEs caused by mutations in CDKL5, DNM1, KCNT1, SCN1A, SCN2A, SCN8A, and UBA5 genes, which present severe pharmaco-resistant epilepsy, are increasingly becoming targets for RNA molecules that aim to restore neuronal excitability and network function." (PMID 41244709, 2025). "Interestingly, evidence of spontaneous seizure activity has recently been described only in heterozygous Cdkl5 +/− female mice, which, therefore, recapitulate features of epilepsy in CDD." (PMID 40903342, 2025). "CDKL5 deficiency disorder (CDD), a developmental encephalopathy caused by mutations in the cyclin-dependent kinase-like 5 (CDKL5) gene, is characterized by a complex and severe clinical picture, including early-onset epilepsy and cognitive, motor, visual, and gastrointestinal disturbances." (PMID 40076840, 2025).
epilepsy (continued). "Furthermore, most studies do not provide participant-level clinical details, extended long-term follow-up, or genetic information to support precision therapeutics, with possible exceptions for SCN8A and CDKL5-related epilepsy." (PMID 40944069, 2025). "We describe several genes-including CDKL5, TSC1/2, SCN1a, and TANC2-that have been associated with epilepsy, ASD, or other NDD phenotypes that play a critical role in regulating one or more stages of brain development or function but differ widely in their disease-causing mechanisms." (PMID 41594775, 2025). "The most distinctive feature of CDD, early-onset epilepsy with intractable seizures, was not recapitulated in newborn or young adult Cdkl5-mutated mice as observed in normal cage conditions up to the age of six months." (PMID 39583831, 2024). "Other genetic epilepsies that can benefit from precision therapy include KCNQ2 (carbamazepine, phenytoin), GLUT1 deficiency, SLC2A1 or CDKL5 (ketogenic diet), PCDH19 (clobazam), mutations in KCNQ2, SCN2A, and SCN8A (ion sodium channel blockers), and mTORopathies (mTOR inhibitors)." (PMID 36980114, 2023). "Further, immature CDKL5-deficient mice do not have seizures or epilepsy and appear insensitive to pro-convulsants such as kainate." (PMID 37490324, 2023). "Finally, there are genes, such as IQSEC2, CDKL5, and NEXMIF, whose alteration causes epilepsy in both sexes." (PMID 38328757, 2023). "It remains unclear whether symptomatic abnormalities are due to chronic CDKL5 dysfunction, acute CDKL5 dysfunction during an earlier critical developmental time point, worsened by epilepsy, or any combination." (PMID 37490324, 2023). "The ketogenic diet (KD) may be effective for patients with CDKL5-related epilepsy, but there is little high-quality evidence to confirm the efficacy." (PMID 36274176, 2022). "Few studies have specifically targeted the efficacy of KD in CDKL5-related epilepsy." (PMID 36274176, 2022). "This meta-analysis investigated the efficacy and safety of KD in CDKL5-related epilepsy." (PMID 36274176, 2022). "Limited strata data could be extracted from the selected papers, other than for cases with “CDKL5” and “have epilepsy”." (PMID 35329122, 2022). "Compared with the efficacy of KD in drug-resistant epilepsy, the definite responder rate to KD in CDKL5-related epilepsy was low (18.% vs. 52.0%), and the literature with low-quality evidence might overestimate the efficacy in our study." (PMID 36274176, 2022). "Therefore, the epilepsy analysis of Cdkl5-knockout mice is slightly challenging and needs to be considered." (PMID 32587608, 2020). "Cyclin-dependent kinase-like 5 (CDKL5) deficiency disorder (CDD) is a severe X-linked neurodevelopmental encephalopathy caused by mutations in the CDKL5 gene and characterized by early-onset epilepsy and intellectual and motor impairments." (PMID 31114483, 2019). "In addition, netrin-G1 and CDKL5, known to bind NGL-1, have been implicated in various brain disorders—netrin-G1 with Rett syndrome, ASD, schizophrenia and bipolar disorder, and CDKL5 with Rett syndrome, epilepsy, intellectual disability, and ASD." (PMID 31680855, 2019). "Despite the presence of numerous neurobehavioral defects, both Cdkl5 KO male and female mice do not show spontaneous epilepsy, a hallmark clinical feature of CDKL5 disorder." (PMID 29977282, 2018). "We were surprised that there were no strong associations between the frequency of seizures or the attainment of gross motor and communication skills and family outcomes, given the major burden of epilepsy and the severe physical and intellectual impairment in the CDKL5 disorder." (PMID 28103894, 2017).
epilepsy (continued). "CDKL5 mutation is an important cause in female patients with early onset epilepsy and severe psychomotor retardation without known etiology." (PMID 24564546, 2014). "Females with RTT-like phenotypes, severe encephalopathy, and very early-onset epilepsy may benefit from a complete analysis of the CDKL5 gene, in terms of both its sequence and its rearrangements." (PMID 22867051, 2012). "We thought that the mother, who has self-limited epilepsy, may not be a carrier of the CDKL5 variant." (PMID 39511144, 2024). "Monogenic epilepsies can be characterized according to the gene function affected: Impaired function of ion channels (e.g., CACNA1A), receptors (e.g., GABRB3), transporters (e.g., SLC2A1), synapse-related (e.g., PRRT2), and other pathways (e.g., CDKL5, PCDH19) are associated with epilepsy." (PMID 38125836, 2023). "Lastly, weak evidence suggested that KD use may reduce the odds ratio of definite responder rate in CDKL5-related epilepsy (pooled OR: 0.225; p-random effects: 0.012) and may reduce the RR of ≥50% seizure reduction: children (pooled RR: 5.641; p-random effects: <0.001) in Drug-resistant epilepsy." (PMID 37836444, 2023). "Moreover, CDKL5, which phosphorylates NGL-1 to promote interactions between NGL-1 and PSD-95 and positively regulates excitatory synaptic structure and function, is associated with Rett syndrome, epilepsy, intellectual disability, and ASD." (PMID 31680855, 2019). "No clear conclusion can be drawn on the role of genotype until even larger studies are undertaken and other previously identified factors (such as epilepsy) are considered, although it does appear as though genotype may have a part to play in the clinical variability in the CDKL5 disorder." (PMID 25657822, 2015). "Interestingly, variants in the 5′UTR of CDKL5 have been identified in some patients affected by CDKL5 deficiency disorder (CDD), a severe loss-of-function monogenic neurodevelopmental syndrome characterized by cognitive disabilities, autistic-like features, refractory epilepsy, and hypotonia." (PMID 37964795, 2023). "The Cdkl5 knockout (KO) mouse model is characterized by ASD features, intellectual disability, and early-onset epilepsy." (PMID 37240625, 2023). "Further, the frequency and severity of seizure activity in patients with single-gene mutations can also be variable, e.g., SCN863, PCDH1964, MEF2C65, CDKL5, and ARX66, which highlights the complexity of modeling rare epilepsy gene candidates." (PMID 34083748, 2021). "Absence of seizures in the KO mice may hinder elucidating the mechanism of epileptogenesis, but it should aid identification of molecular roles of CDKL5 in physiological functions, owing to the absence of neuronal loss or damage secondarily caused by the excitotoxicity associated with epilepsy." (PMID 29702698, 2018).
epilepsy (continued). "The efficacy of KD in CDKL5-related epilepsy is still not clear, so we performed a meta-analysis based on previous studies to collect evidence regarding the efficacy of KD and to provide a basis for the treatment of these patients." (PMID 36274176, 2022). "Meta-analysis revealed that the definite responder rate to KD in the treatment of CDKL5-related epilepsy was 18.0% [95% CI (0.07, 0.67)], with no statistical heterogeneity among studies (I2 = 0%, P = 0.45)." (PMID 36274176, 2022). "Despite the lack of overt epilepsy, Cdkl5 KO mice exhibit numerous behavioral deficits across motor, sensory, cognitive, and socioemotional domains that are reminiscent of human symptomatology." (PMID 29977282, 2018). "Both miRNAs regulate genes central to neuronal excitability, synaptic dysfunction, and neuroinflammation, which are core mechanisms underlying epilepsy and CDD, although none of the specific targets are clearly reported yet as established, validated downstream effectors of CDKL5 in CDD." (PMID 41301530, 2025). "It is worth to note, however, that the epilepsy prevalence was not different between wild-type and Cdkl5 +/− mice; this may be due to the old age of mice suggesting that at least some of these seizures were age-dependent idiopathic seizures." (PMID 40903342, 2025). "However, the quality of the evidence was poor because the data came from a retrospective observational study with a relatively large sample size, and the efficacy of KD in CDKL5-related epilepsy was not clear." (PMID 36274176, 2022). "The prior infantile epilepsy panel had included exon‐level array CGH for CDKL5, however, mosaic events may not be detected by exon aCGH." (PMID 33955715, 2021). "Among the triplosensitive genes located in the duplicated region, ARX, CDKL5, CNKSR2, MID1, PTCHD1, RPS6KA3, and SMS are known to be involved in intellectual developmental disorders with/without epilepsy." (PMID 39062680, 2024). "These two cases present with a CDKL5 and PCDH19 phenotype, respectively, rather than the common features of KS in terms of onset age, epilepsy type, and hypogonadism." (PMID 37479950, 2023).